CXCL8 (C-X-C motif chemokine ligand 8)
Diseases named in the same sentence as CXCL8 in open-access papers (continued):
Sharing a sentence is not in itself a finding about the gene and the disease.
bacterial infection (230 papers, 2008 to 2026). "During SARS-CoV-2 infection, CXCL8 levels are increased in blood and alveoli; the increase is also associated with bacterial infection." (PMID 38543303, 2024). "Respiratory epithelial cells producing low levels of DNMT3B expressed higher levels of CXCL1 and CXCL8, which was associated with increased neutrophil recruitment during bacterial infections." (PMID 36078063, 2022). "In this context, the response of neutrophils to CXCL-8 is essential for the control of bacterial infections, avoiding complications caused by coinfection with Plasmodium." (PMID 24741587, 2014). "The upregulation of pro-inflammatory cytokines, including CXCL8, CXCL10, IL-1β, IL-6 and MMP9 was associated with the progression of host bacterial infection." (PMID 40839565, 2025). "Upon activation by factors like bacterial infections, NF-κB translocates to the nucleus, binds to the CXCL8 gene promoter, and enhances its transcription." (PMID 39717557, 2024). "IL-8 (CXCL8) is a neutrophil chemoattractant that plays a central role in innate immunity to bacterial infection." (PMID 33442048, 2021). "The heat map showed that the gene expression levels of 62 DEGs were upregulated and that some of these genes, such as IL-6, IL-1β, CCL2, CXCL2, CXCL8, and CSF3, are closely associated with host defense responses to bacterial infection." (PMID 31737164, 2019). "Inflammatory activation of epithelial and endothelial cells, e.g. after bacterial infection, induces the release of interleukin-8 (IL-8/CXCL8) and other chemokines that recruit polymorphonuclear neutrophils (PMN)." (PMID 23305147, 2013). "CXCL8 (also known as interleukin-8), one of the best-characterized members of the chemokine family, recruits neutrophils under such conditions as bacterial infection and tissue injury." (PMID 20668677, 2010). "Our findings that ASMC can respond directly to Gram-negative and Gram-positive bacteria by releasing the neutrophil selective chemokine, CXCL-8, is consistent with what we know about the role of neutrophil recruitment in bacterial infections in the lung." (PMID 18380907, 2008). "CXCL8 also serves to attract T cells, dampening tissue inflammation in response to bacterial infection, such as C. perfringens, through NF-κB signaling pathway, chemokine signaling pathway, NOD-like receptor signaling pathway and Toll-like receptor signaling pathway." (PMID 31114763, 2019). "CXCL8 is an important inflammatory mediator regulated by NF-κB transcription factor and serves to modify and enhance human innate immune responses in defense against bacterial infections." (PMID 31114763, 2019). "We use EBLs routinely for bacterial infections studies so we investigated whether these cells were able to produce CXCL8 following addition of H7 flagellin." (PMID 25827709, 2015). "This suggest that PRRSV may inhibit intracellular ROS production of MDMs during bacterial infections.Another set of studies sought to determine whether TUL inhibition of the viral-induced pro-inflammatory CXCL-8 coincided with an increase in anti-inflammatory signaling." (PMID 31442273, 2019). "Bacterial infections provoke the release of pro-inflammatory factors, such as prostaglandins and cytokines, e.g., interleukin 1A (IL1A), interleukin 1 B (IL1B), and C-X-C motif chemokine ligand 8 (CXCL8)." (PMID 33748222, 2021). "Consistent with this, patients with amputations resulting from combat wounds showed increased serum levels of CCL3 and CCL4 as well as increased CXCL8, CCL3, and CCL4 in the wound effluent due to bacterial infection." (PMID 30340330, 2018). "SRNA52320 down-regulated all detectable proteins in the LPS-stimulated MAPK signaling pathway, which IPA predicts to result in decreased IL-8 (CXCL8) levels, a reduced innate immune response, and consequently increased bacterial infection." (PMID 27295279, 2016).
bacterial infection (continued). "had higher expression of IL6 and C-X-C motif chemokine ligand 8 (CXCL8) following the LPS challenge, indicating that laminarin might provide improved protection against intestinal bacterial infection via enhanced activation of the immune system." (PMID 34573610, 2021). "The mRNA levels of IL-1β and CXCL8 that were induced by bacterial infection were not changed in the presence of both pathogens." (PMID 28195157, 2017). "Systemic analysis of chemokines in combat wounds infected with <105 colony forming units (CFU) of bacteria were found to have increased serum levels of CXCL10, CXCL8, and CCL3 compared to combat wounds without bacterial infection." (PMID 30340330, 2018).
inflammation (157 papers, 2005 to 2026). Aberrant reaction of the microcirculation characterized by movement of fluid and leukocytes from the blood into extravascular tissues. "In response to allergens, activation of LPS receptor TLR4 on lung epithelial cells can stimulate CXCL8 chemokine secretion to recruit neutrophil to the lung in association with increased eosinophilic inflammation, IgE, Th2 cytokines and mucus secretion." (PMID 33195308, 2020). "In addition, this could explain why those dogs carrying the TLR5 RP haplotype produce significantly less CXCL8 and are therefore less susceptible to the development of chronic intestinal inflammation such as in IBD." (PMID 22279566, 2012). "Within the molecules analyzed as SASP, IL-8/CXCL8 is known to exert a crucial role in lung inflammation in vivo." (PMID 38799687, 2024). "A clinical study reported reduced CXCL8 levels and improved clinical appearance in patients with mild oral inflammation after the use of chewing gums containing Lactobacillus reuteri." (PMID 32429151, 2020). "Active DD lesions (M1 and M2 and reactivated M4.1) were characterized by acute ulcerative inflammation, increased Cxcl-8, TLR4, and β-defensin gene expression, and the presence of abundant spirochetes." (PMID 30072966, 2018). "CXCL-8 is an important chemotactic cytokine in human lung inflammation, therefore, we focused on the mechanism of CXCL-8 release from BEAS-2B cells." (PMID 28335387, 2017). "The CXCL8/IL-8 axis aligns with but extends prior findings on synovial inflammation in OA." (PMID 40672822, 2025). "Despite the fact that both CXCL8 and MMP-9 are important factors associated with neutrophilic airway inflammation, there are few therapeutic agents for these factors involved in neutrophilic airway inflammation." (PMID 32823491, 2020). "Higher levels of Matrix metallopeptidase (MMP-12), C-X-C motif chemokine ligand-8 (CXCL8), neutrophil elastase, azurocidin 1 (AZU-1), and pro-platelet basic protein (PPBP) were observed in the sputum of ex-smoking asthmatics, which are linked to neutrophilic inflammation." (PMID 37367073, 2023). "Moreover, the presence of ILC-like cells expressing CCL4 and CXCL8 may contribute to the effects of the cNK cells in the perpetuation of liver inflammation since these chemokines are chemoattractants for neutrophils and immature dendritic cells." (PMID 37063898, 2023). "In a model of organic dust-induced airway inflammation, TLR2 knockout mice had significantly lower airway neutrophils, IL-6, TNF-α, and CXCL-1 (mouse homolog of CXCL8) compared with wild-type controls suggesting that airway inflammation is dependent on TLR2." (PMID 23606791, 2013). "Interleukin-8 (IL-8, CXCL8) is a potent chemoattractant for neutrophils and contributes to acute liver inflammation." (PMID 21731723, 2011).
cardiovascular disease (78 papers, 2008 to 2026). "Previous studies have reported a reduction of plasma chemokines (i.e CCL2, CCL4, CXCL8) in patients with cardiovascular disease treated with statins." (PMID 19421322, 2009).
infectious disease (41 papers, 2011 to 2025). A disorder directly resulting from the presence and activity of a microbial, viral, or parasitic agent in humans. "In humans, the gene polymorphism studies indicate that regions within the gene, others than promoter region, may contribute to CXCL8 production and, potentially, susceptibility to certain infectious diseases." (PMID 29742137, 2018). "CXCL8 plays an important role in inflammatory responses, leukocyte chemotaxis, and infectious diseases." (PMID 34233297, 2021).
respiratory diseases (37 papers, 2012 to 2025). "In Chinese Erhualian pigs, QTLs affecting respiratory disease were identified by a genome-wide association study; CXCL6, CXCL8, KIT, and CTBP2 were highlighted as candidates that might associated with resistance or susceptibility to swine enzootic pneumonia-like respiratory disease." (PMID 31656701, 2019).
adenocarcinoma (36 papers, 2006 to 2025). A common cancer characterized by the presence of malignant glandular cells. "Of these, CXCL2 has previously been shown to be regulated by NFAT in microglia, and Cxcl8 expression was reported to depend on NFAT in adenocarcinoma cells." (PMID 25550437, 2015). "To compare human ASC response with CXCL1 and CXCL8, we used conditioned medium from human DU145 adenocarcinoma cells that secrete both chemokines." (PMID 27241286, 2016).
immune dysfunction (26 papers, 2012 to 2025). "The immune dysfunction mainly contributes to the pathogenesis of PCHD, and three ceRNA networks of CD83, CXCL8, and NR4A2 may be potential candidate biomarkers for early diagnosis and treatment targets of PCHD." (PMID 36093144, 2022).
metabolic disorders (25 papers, 2015 to 2025). "Inhibition of the CXCL8/CXCR1 axis can protect db/db mice from metabolic diseases by regulating inflammation, as well as reducing the inflammation and apoptosis of diabetic renal tubular cells induced by high glucose." (PMID 36675322, 2023).
hematological malignancies (19 papers, 2017 to 2025). "Since CXCL8 plays an important role in hematologic malignancies, we focused on CXCL8 for further study." (PMID 39706835, 2024). "As long as CXCL16 is found in the BM at high levels and CXCL8, the CXCR1, and CXCR2 ligand is significantly elevated in MM, CLL, AML, and MDS patients, the targeting of CXCL16-CXCR6 and IL8-CXCR2/CXCR1 pathways should be studied in depth for hematologic malignancies." (PMID 35990652, 2022).
psychiatric disorder (19 papers, 2016 to 2026). A disorder characterized by behavioral and/or psychological abnormalities, often accompanied by physical symptoms. "Chemokines like CCL2 and CXCL8 are upregulated, guiding immune cell migration to both the skin and brain, contributing to skin inflammation and psychiatric disorders." (PMID 41393358, 2026).
retinopathy (17 papers, 2012 to 2025). "In addition, we have demonstrated that IL-6 strongly correlates with chemokines in the diabetic group (r=0.74 for CCL2; r=0.86 for CXCL8), indicating that the increased levels are likely downstream effects of elevated IL-6 seen in eyes with retinopathy." (PMID 22511846, 2012). "ELR+ CXC chemokines, including CXCL8 and CXCL2, are elevated in the vitreous body of diabetic patients with proliferative retinopathy." (PMID 36511116, 2023).
neurodegenerative disease (16 papers, 2015 to 2025). A disorder of the central nervous system characterized by gradual and progressive loss of neural tissue and neurologic function. "The role of estradiol is not fully understood, but studies have shown that estradiol plays an important role in neurodegenerative diseases in an anti-inflammatory fashion, since estradiol can upregulate the synthesis and secretion of inflammatory factors, e.g., TNFα, CXCL-8, IL-8, and IL-6." (PMID 35370702, 2022).
heart disease (14 papers, 2013 to 2024). "Higher CXCL10 and CXCL8 levels detected in patients with different cardiac diseases vs. healthy subjects likely reflect early inflammatory processes, differently from classical biomarkers, which reveal already established damages." (PMID 39355618, 2024). "This is the case of the chemokines CXCL10 and CXCL8, classified as ERL- and ERL+, based on absence or presence of Glut-Leu-Arg motif, both molecules with multifaceted functions in disease development, widely engaged in cardiac disease initiation and progression." (PMID 39355618, 2024).
liver (7 papers, 2005 to 2024). "The forest plot shows the univariate results of CXCL8 in different gastrointestinal tumors, and the KM curve shows that the effect of CXCL8 on prognosis in different gastrointestinal tumors." (PMID 36698399, 2022).
hematologic cancers (6 papers, 2015 to 2025). "Within the hematologic cancer patient cohort there was a striking increase in the levels of the chemokines CCL2, CCL3, CCL4, CXCL8, and the cytokine IL-1β, in the Severe-Death group compared to the Mild group." (PMID 36700209, 2022). "While CXCL8 and IL-6 were the most important factors that segregated Severe-Death solid tumors patients, CXCL8, CRP and IL-6 had important roles for segregation of patients with hematologic cancers." (PMID 36700209, 2022).
CNS tumors (3 papers, 2020 to 2026). "Furthermore, cerebrospinal fluid (CSF) levels of CXCL8 were significantly elevated in patients with CNS tumors as compared to non-tumoral control group." (PMID 32456359, 2020).
animal disease (1 paper, 2010). "Neutrophil levels observed at 6 h for the dimer are comparable to those observed in animal disease models, indicating an obligatory role for CXCL8 dimerization." (PMID 20668677, 2010).
gynaecological disease (1 paper, 2021). "Additionally, the roles played by polyomaviruses in the induction of gynaecological disease in CXCL8 dependent manner have also been demonstrated by Zhang and colleagues." (PMID 34082771, 2021). "Based on the fact that CXCL8 is the main chemotactic factor for neutrophils, it may be hypothesized that polyomaviruses induce gynaecological diseases by increasing inflammation in neutrophil dependent manner." (PMID 34082771, 2021).
CXCL8 also shares sentences with these, for which no sentence is quoted: inflammatory bowel disease (85 papers); metabolic syndrome (53); myocardial infarction (50); chronic periodontitis (45); anemia (35); sarcopenia (35); bacteremia (32); idiopathic pulmonary fibrosis (28); lymphopenia (28); urinary tract infection (28); neuroblastoma (27); encephalitis (26); thrombosis (26); septic shock (24); Pleural effusion (23); type 1 diabetes (23); pancreatitis (22); adenoma (21); colorectal adenocarcinoma (20); Peptic ulcer (20); Erythema (19); multiple myeloma (19); myocardial ischemia (19); neurological diseases (19); pulmonary edema (19); cognitive decline (18); macular edema (18); Oral leukoplakia (18); Shock (18); acute myocardial infarction (17).
A further 918 diseases each share a sentence with CXCL8 in 17 papers or fewer.